FAM240A (family with sequence similarity 240 member A)
Gene: Protein-coding gene on chromosome 3 (46,612,525 to 46,626,543, forward strand). Ensembl gene ENSG00000283473.
Genetic constraint (gnomAD): Loss-of-function variants: 6 observed, 4.35 expected, observed/expected ratio (o/e) 1.38, 90% interval 0.71 to 1.92. That is too few expected variants to judge how well the gene tolerates losing a copy. Missense variants: 39 observed, 42.32 expected, observed/expected ratio (o/e) 0.92, 90% interval 0.71 to 1.2. Synonymous variants: 9 observed, 13.59 expected, observed/expected ratio (o/e) 0.66, 90% interval 0.4 to 1.15.
Homologues: Orthologues: chimpanzee FAM240A (99% identical), macaque FAM240A (95% identical), pig FAM240A (89% identical), dog FAM240A (83% identical), rabbit FAM240A (80% identical), mouse Fam240a (78% identical), guinea pig FAM240A (70% identical). Paralogues in human: FAM240B (60% identical).